HDAC5 (histone deacetylase 5)
Diseases named in the same sentence as HDAC5 in open-access papers (continued):
Sharing a sentence is not in itself a finding about the gene and the disease.
hepatocellular carcinoma (18 papers, 2014 to 2026). A malignant tumor that arises from hepatocytes. "Recent studies have reported the aberrant overexpression of HDAC5 in hepatocellular carcinoma and high-risk medulloblastoma, whereas HDAC5 downregulation has been reported in colon cancer and is associated with poor prognosis in lung cancer patients." (PMID 27177225, 2016). "Moreover, HDAC5 was implicated in resistance to sorafenib, a multi-tyrosine kinase inhibitor, in hepatocellular carcinoma cells." (PMID 40290805, 2025). "Nowadays, research has shown that hepatocellular carcinoma and high-risk medulloblastoma exhibit aberrant overexpression of HDAC5, while colon cancer and lung cancer patients’ poor prognosis are linked to HDAC5 downregulation." (PMID 40077783, 2025). "In addition, loss of HDAC5 restrains the cell proliferation of hepatocellular carcinoma by regulation of p21 and cyclin D1, thereby leading to cell cycle arrest and apoptosis." (PMID 25546298, 2014). "In an in vitro WD model, copper-loaded hepatoma G2 (HepG2) cells also demonstrated reduced HDAC5 levels compared with control, indicating a direct effect of copper on reduced HDAC5 levels, independent from hepatic inflammation or fibrosis." (PMID 34098115, 2021). "The apoptotic effects of HDAC5 has been reported previously in a study showing that HDAC5 overexpression promotes proliferation but decreases caspase-dependent apoptosis in hepatocellular carcinoma cell lines." (PMID 34021541, 2021). "Taken together, these results demonstrate for the first time that AR-42 targets HDAC5 and induces apoptosis in human hepatocellular carcinoma cells." (PMID 26993777, 2016). "In the present study, we confirmed high levels of HDAC5 in tumor tissues, which suggested the poor survival in patients with hepatocellular carcinoma." (PMID 26993777, 2016). "Additionally, expression changes of HDAC5 were found, e.g., in hepatocellular carcinoma, lung cancer, and colon cancer, thus underlining its role in oncogenesis." (PMID 30321986, 2018). "In human hepatoma cells, AMPK-activated histone deacetylase 5 (HDAC5) deacetylated HSP70, which, in turn, mediated the HSP90-HIF-1α interactions, followed by the nuclear translocation of HIF-1α and induction of the HIF-1-dependent transcription response." (PMID 33806538, 2021). "In this article, we aimed to explore the potential protective effect of curcumin against UV radiation-induced DNMT1, DNMT3A, DNMT3B, HDAC5, and HDAC6 expression in immortalized keratinocytes (HaCaT), hepatocellular carcinoma (HepG2), and lung adenocarcinoma (A549) cells." (PMID 41901340, 2026). "Whereas HDAC7, and to a lesser extent HDAC4, appear to repress HBV transcription, HDAC5 upregulated HBV capsid abundance and supported enhanced HBV biosynthesis in both hepatoma and nonhepatoma cells." (PMID 32822428, 2020).
depression (16 papers, 2014 to 2025). "The NAc is implicated in depression, and abnormal expression of HDACs such as HDAC5 and HDAC2 has been observed in the NAc." (PMID 33574772, 2020). "The reason why HDAC5 plays opposite roles in different brain areas may lie in its involvement in diverse complexes that target specific gene subsets associated with depression." (PMID 37644009, 2023). "Thus, further studies on other HDAC isoforms associated with depression are needed to demonstrate the specificity of changes in HDAC5 expression." (PMID 33672075, 2021). "In particular, HDAC5 may be associated with depression in several types of HDAC subtypes." (PMID 32878311, 2020). "Thus, this may allow for overexpression of HDAC5, and via its association with stress and depression, should repress Bdnf promoter IV activity." (PMID 29963072, 2018). "Administration of VPA furthermore prevented increased HDAC5 expression as well as anxiety- and depression-like behavior induced by chronic unpredictable stress (see 3.3.2." (PMID 36946487, 2024). "In a clinical study, HDAC5 expression was found to have increased in the blood of patients with depression." (PMID 32878311, 2020). "Studies indicate that HDAC5 downregulation may be crucial for the therapeutic efficacy of imipramine in depression models, implying that targeting HDAC5 could yield new antidepressant options." (PMID 40149919, 2025). "Importantly, increased expression of HDAC5 protein has already been found in an animal model of depression, and lowering the level of this enzyme by antidepressants is critical for their therapeutic effect." (PMID 38194217, 2024). "Moreover, decreased histone acetylation with increased HDAC5 levels was found at the GR exon I7 promoter in a model of depression-like behavior." (PMID 37358267, 2023). "HDAC5 seems to play a role of promoting depression in the hippocampus, but in other brain regions, HDAC5 may have the opposite effect." (PMID 37644009, 2023). "Hdac5 overexpression blocks the enhanced H3K9/K14ac and Bdnf splice variant expression responses to the antidepressant imipramine, suggesting a potential for HDAC inhibitors in the treatment of depression." (PMID 28360846, 2017). "HDAC5 has also been shown to be involved in major depression." (PMID 25322459, 2014). "This suggests a role for HDAC5 expression in the systemic pathophysiology of major depression." (PMID 25322459, 2014). "Thirdly, it is revealed that detecting the role of manipulating HDAC5 in the behavioral adaptations to chronic emotional stimuli provides strong evidence to support the effects of HDAC5 in the pathogenesis of drug addiction, depression, and other stress-related syndromes." (PMID 33574772, 2020). "Generally, in these animal models of depression, HDAC2 and HDAC5 were elevated in the Hp but decreased in the nucleus accumbens." (PMID 35011254, 2021). "Previous studies have found that the mRNA levels of HDAC5 and CREB in patients with depression were significantly higher than those in the control group, and their mRNA levels decreased after antidepressant treatment, indicating the importance of these two genes in depression." (PMID 36911124, 2023).
lung carcinoma (16 papers, 2016 to 2025). "HDAC5 is overexpressed in several cancers, including colorectal, breast, and lung cancer and neuroblastoma, and silencing of HDAC5 has been shown to reduce cancer cell motility and invasion." (PMID 38461415, 2024). "Fentanyl inhibits lung cancer viability and invasion via repression of HDAC5 CDKN1A upregulation and cisplatin‐pemetrexed resistance in non‐small cell lung cancer cells." (PMID 39236027, 2024). "Among them, HDAC5 (histone deacetylase 5), as a member of the class IIa family of HDACs, is a well-known oncogene in numerous cancer types, including lung cancer." (PMID 36819033, 2023). "Considering the tumor-promoting role of HDAC5, we further reasoned if HDAC5 silencing would abrogate the S. maltophilia induced cell proliferation and migration in lung cancer cells." (PMID 36819033, 2023). "Consistent with our data from the mouse model, we also found S. maltophilia induced HDAC5 expression in lung cancer cells." (PMID 36819033, 2023). "Overexpression of HDAC5 increased the proliferation of lung cancer cells, possibly via upregulation of downstream target genes." (PMID 34178647, 2021). "HDAC5 was also shown to promote cell invasion and metastasis in neuroblastoma, pancreatic cancer and lung cancer." (PMID 34178647, 2021). "Relating to the mechanisms of LMK-235’s cytotoxic action, studies performed on lung cancer cells indicate that HDAC5 inhibition with LMK-235 interferes with the ERK-1/2 pathway involved in the differentiation of cancer stem cells." (PMID 30321986, 2018). "In summary, our findings suggest that combination therapy targeting HDAC5 may offer significant benefits for EGFR-mutant lung cancer patients treated with osimertinib." (PMID 40290805, 2025). "Since previous reports demonstrated oncogenic roles of HDAC5 in various cancers such as breast, liver, colon, and lung cancer, we hypothesized that inhibition of HDAC5 induction might affect the cellular tolerance to osimertinib." (PMID 40290805, 2025). "We further screened the candidates showing more than 2-fold upregulation in other lung cancer cell lines, H1975 (L858R and T790 M EGFR mutation) and PC9 (delR746-A750 EGFR mutation) cells treated with 100 nM osimertinib, and identified HDAC5, one of histone deacetylases." (PMID 40290805, 2025). "HDAC5 was also shown to promote cell invasion and metastasis in lung cancer." (PMID 36819033, 2023). "Further, HDAC5 displays a significant upregulation in lung cancer and increases the proliferation and invasion of lung cancer cells through the upregulation of DLL4 (Delta-like protein 4), Notch-1 (Neurogenic locus notch homolog protein 1) and Twist-1 (Twist-related protein 1)." (PMID 35626663, 2022). "HDAC5 showed elevated expression in tumorspheres formed by H460 lung cancer cells." (PMID 34178647, 2021). "In this study, we performed a microarray screening and identified HDAC5, a class IIa HDAC, which was rapidly upregulated by osimertinib in EGFR-mutant lung cancer cells." (PMID 40290805, 2025). "It was recently demonstrated that HDAC5 together with HDAC4 enhanced glycolysis by inducing the upregulation of hexokinase 2 (HK2), which was critical for EMT induced by hypoexpression of 5′ AMP-activated protein kinase (AMPK) in lung cancer." (PMID 34178647, 2021). "Application of the HDAC5 inhibitor LMK-235 reduced extracellular signal-regulated kinase 1/2 (ERK1/2) phosphorylation in a dose-dependent manner, demonstrating that the HDAC5-ERK1/2 axis plays an important role in maintaining the stemness of lung cancer stem cells." (PMID 34178647, 2021). "Besides, CCR7, CST7, GPR143, HDAC5, and IDO1 are also related to lung cancer or the MAPK pathway." (PMID 30972101, 2019).
pancreatic cancer (11 papers, 2012 to 2025). "In pancreatic cancer, HDAC5 inhibits the binding of GATA1 to the promoter region of the downstream gene PLA2G4A by deacetylating the transcription factor GATA1." (PMID 40781327, 2025). "Taken together, our data indicated the synergistic effect of HDAC5 inhibition and anti-PD-1 treatment in immunotherapy resistant pancreatic cancer." (PMID 35265200, 2022). "Most genes have been related to diabetes and cancer, with most of them being linked to pancreatic cancer (CEACAM6, HDAC5, HPCAL1, PARVG, and STYXL1)." (PMID 36360783, 2022). "Allografts of pancreatic cancer in mouse were applied to test the efficiency of HDAC5 inhibition and anti-PD1 co-treatment." (PMID 35265200, 2022). "Given the role of HDAC5 in modulating the expression PD-L1 in pancreatic cancer cells, we next assessed the potential clinical benefit of HDAC5 inhibition in pancreatic cancer patients treated with ICB." (PMID 35265200, 2022). "In this study, we identified HDAC5 was a key regulator of PD-L1 through mediating the deacetylation of NF-κB p65 in pancreatic cancer." (PMID 35265200, 2022). "And HDAC5 knockdown in 2 different pancreatic cancer cell lines (Mia PaCa-2 and PANC-1) using 2 independent shRNAs increased PD-L1 mRNA and protein levels." (PMID 35265200, 2022). "This interaction between HDAC5 and p65 was confirmed at the endogenous level in pancreatic cancer cell line." (PMID 35265200, 2022). "Upregulated genes in patients harboring HDAC5 deletions were enriched in adaptive immune responses and lymphocyte-mediated immunity in The Cancer Genome Atlas (TCGA) pancreatic cancer dataset." (PMID 35265200, 2022). "Consistent with our findings in human pancreatic cancer cells, Hdac5 silencing in Panc02 murine pancreatic cancer cells upregulated Pd-l1." (PMID 35265200, 2022). "Simvastatin was shown to attenuate pancreatic cancer growth by inhibiting the oxysterol binding-related protein 5 (ORP5)/HDAC5 axis." (PMID 34178647, 2021). "Western blotting revealed that the majority of classes I and II HDACs (except for HDAC5) were readily detected in the pancreatic cancer cell lines, rendering them the potential to be involved in pancreatic cancer cell growth and/or survival." (PMID 23251689, 2012). "HDAC5 inhibition thus sensitized pancreatic cancer to PD-1 blockade." (PMID 38540967, 2024). "HDAC5, a member of class II HDAC family, has been found to regulate PD‐L1 expression by stimulating p65 deacetylation in pancreatic cancer." (PMID 41267925, 2025). "Though the exact pathways leading to PD-L1 regulation by class II HDACs have not been fully elucidated, data derived from studies in pancreatic cancer demonstrate that HDAC5 negatively regulates PD-L1 expression via interaction with NF-κΒ p65." (PMID 38672128, 2024). "Furthermore, knockdown of histone deacetylase 5 (HDAC5) results in notable activation of NF-κB signaling, thus significantly increasing PD-L1 expression in pancreatic cancer (PC)." (PMID 35907881, 2022). "Another study demonstrated that HDAC5 recruited macrophages to the tumor microenvironment through the Suppressor of cytokine signaling 3 (Socs3)/C-C motif chemokine ligand 2 (CCL2) axis and promoted pancreatic cancer via TGF-β-dependent paracrine signaling." (PMID 34178647, 2021). "HDAC IIa composes of HDAC4, HDAC5, HDAC7, and HDAC9, numbers of studies demonstrated HDAC IIa inhibition as an alternative approach to avoid the progression of various diseases, examples like breast tumors, pancreatic cancer, multiple myeloma, and type 2 diabetes." (PMID 35492337, 2022). "Additionally, Class IIa members, HDAC-5 and -9, have been found to correlate with poor survival rates in medulloblastoma cases, while HDAC-7 overexpression has been related to significantly higher number of deaths and recurrences in pancreatic cancer." (PMID 33799478, 2021). "Interestingly, the majority of class IIa HDACs (except for HDAC5) were detected in almost all the pancreatic cancer cell lines but not in the HPDE cells." (PMID 23251689, 2012).
medulloblastoma (10 papers, 2013 to 2025). A malignant, invasive embryonal neoplasm arising from the cerebellum. "For example, HDAC5 overexpression was shown to promote cell growth, while small interfering RNA (siRNA)-mediated silencing of HDAC5 caused cell cycle arrest at the G0 phase in medulloblastoma." (PMID 34178647, 2021). "HDAC5 and HDAC9 are valuable markers for medulloblastoma risk stratification and are potential novel drug targets." (PMID 27177225, 2016). "In medulloblastoma patients, aberrant expression of HDAC5 and HDAC9 have been correlated with poor clinical outcome." (PMID 23951168, 2013). "In human medulloblastoma, HDAC5 and HDAC9 upregulation were identified as markers for tumors with poor prognosis." (PMID 23951168, 2013). "Recent studies have suggested that HDAC5 and HDAC9 are significantly upregulated in high-risk medulloblastoma in comparison with low-risk medulloblastoma and be associated with poor survival 6.It also has been reported that HDAC2 expression is significantly associated with CRC progression." (PMID 35399729, 2022). "In medulloblastoma, HDAC5 and HDAC9 up-regulation has been associated with poor prognosis and HDAC inhibitor treatment resulted in down-regulation of the Dickkopf-1 tumor-suppressor through antagonizing Wnt signaling in cultured medulloblastoma cells." (PMID 23951168, 2013). "HDAC5 and HDAC9 expression rise in high-grade medulloblastoma, compared to low-grade medulloblastoma and abnormal tissues." (PMID 36146527, 2022). "H3 acetylation levels are elevated in high-grade astrocytoma compared to low-grade medulloblastoma and normal brain tissues, as are the expression of HDAC5 and HDAC9 in high-grade medulloblastoma." (PMID 30498431, 2018).